CXCR3 (C-X-C motif chemokine receptor 3)
Diseases named in the same sentence as CXCR3 in open-access papers (continued):
Sharing a sentence is not in itself a finding about the gene and the disease.
urothelial bladder carcinoma (1 paper, 2022). "In conclusion, from analyzing publicly available datasets and our own clinical immunohistochemistry specimens, we conclude that higher levels of CXCR3 pathway activation are correlated with a better response to immunotherapy in patients with urothelial bladder carcinoma." (PMID 35562800, 2022). "To investigate the clinical significance of CXCR3 pathway activation and response to immunotherapy in patients with urothelial bladder carcinoma, we performed immunohistochemical analysis on two urothelial carcinoma patients treated with ICI therapy at Zhujiang hospital." (PMID 35562800, 2022).
vaginal infection (1 paper, 2017). "Even though CXCR3−/− mice eventually are able to clear up infection in time as WT, there is no overall delay for CXCR3−/− mice to clear a vaginal infection compared to WT." (PMID 29552679, 2017).
tumor (1,012 papers, 2003 to 2026). "Although CXCR3 has been linked to tumor dissemination in multiple cancers, its impact appears to be context- and tumor-dependent." (PMID 41129238, 2026). "In multiple cancer types, elevated CXCL9/CXCR3 signaling has been associated with improved prognosis, primarily due to effective tumor-immune cell interactions that curb tumor progression." (PMID 40557143, 2025). "Hetero-oligomerization with CXCR4 induces negative binding cooperativity—CXCL12 binding to CXCR4 suppresses CXCL11-mediated CXCR3 activation, a mechanism implicated in tumor immune evasion." (PMID 40786052, 2025). "Taken together, these results suggest that T-cell maturation within the tumor involves programmed, sequential co-expression of CXCR3, CCR5 and CXCR6 followed by a gradual loss of these receptors in the terminally differentiated phase." (PMID 41415437, 2025). "CXCR3, a chemokine receptor essential for T cell and NK cell migration to tumor sites, is closely associated with effector immune responses." (PMID 40484866, 2025). "Together, the findings revealed that Hmgb2 deficiency–induced tumor regression depended on STAT1/CXCL10/CXCR3 pathway." (PMID 40315321, 2025). "According to our sequencing data and TCGA database, CXCL10 and CXCR3 gene expression was strongly associated with favourable prognosis and the abundance of tumour‐infiltrating CD8+ T cell populations." (PMID 39219056, 2025). "High CXCR3 expression on tumor cells is associated with advanced tumor grade and metastatic progression." (PMID 41516196, 2025). "Higher levels of CXCL10 in NSCLC is associated with better prognosis by the recruitment of CXCR3+ CD8+ T cells to the tumour sites." (PMID 40852716, 2025). "As its expression is also associated with a Th1 like phenotype and CXCR3 is shown to promote migration of T cells into tumor tissue in vitro, it is a relevant surface molecule for evaluating the results of our stimulation procedure." (PMID 41369406, 2025). "Taken together, our data highlight a CXCR3-associated anti-tumor immune program already in the treatment-naïve TiME that appears to “prime” patients for extended responses to second-line CTX." (PMID 40696453, 2025). "A comprehensive understanding of CXCR3 variants and their distinct signalling pathways is essential for evaluating their potential as anti-tumour targets and for developing variant-specific drugs for combination therapies." (PMID 40361472, 2025). "CXCL10 is a secreted chemokine that is involved in trafficking of CXCR3-positive leukocytes, including CXCR3+ tumor associated CD8+ T cells and natural killer cells that promote tumor suppression as well as immunosuppressive CXCR3+ Tregs." (PMID 40589738, 2025). "And HDAC3‐deficient HCC cells recruited CXCR3+ T cells into the tumor microenvironment to inhibit tumor growth." (PMID 38783893, 2024). "Low levels of CXCR1 and CXCR3 are associated with a decreased tumor volume, decreased alpha fetoprotein levels, and a decreased TNM tumor stage 110." (PMID 38481800, 2024). "In HER2+ breast cancer, the combination of palbociclib and trastuzumab (anti-HER2) achieves anti-tumor efficacy by stimulating the release of CXCR3-reactive chemokines and increasing the recruitment of tumor-associated natural killer (NK) cells." (PMID 39620228, 2024). "The results suggest that the prostate has a unique environment that promotes local CXCL10 synthesis, which is crucial for attracting CXCR3+ effector cells to tumor-associated TLO." (PMID 38745115, 2024). "The expression of CXCL9 by tumor-associated macrophages regulates the recruitment and positioning of CXCR3+ CD8 T cells, underlying the clinical response to anti-PD(L)-1 treatment." (PMID 39076974, 2024). "Elevated levels of CXCL10 were associated with tumor-infiltrating CXCR3+ immune cells, including activated T cells, macrophages, DCs, monocytes, and NK cells." (PMID 39080467, 2024).
tumor (continued). "The application of IFNγ neutralizing antibodies, knockdown of CXCL9/CXCL10 gene, or CXCR3 blockade of macrophages all cause the attenuation of anti-tumor immune response." (PMID 38787372, 2024). "Another mechanism involves the inhibition of CD8+ T cell migration to tumor beds by TGF-β-mediated silencing of the gene encoding C-X-C chemokine receptor 3 (CXCR3)." (PMID 39004699, 2024). "Following this intervention, we noted that the CXCR3 blockade led to the abrogation of the anti‐tumor efficacy caused by Sin3B deficiency." (PMID 39316363, 2024). "We have shown that high density and expression of CXCR3 is associated with advanced tumor stage and poorer RFS in surgically treated RCC." (PMID 36831346, 2023). "In contrast, the progressive loss of Cxcr3+ tetramer + T cells in tumor corresponded to an accumulation of Cxcr3-Klrg1- cells, a subset not previously identified in the chronic infection model." (PMID 36472588, 2023). "CXCR3 and its ligand expression levels are also associated with prognosis, metastatic risk and tumour growth in ccRCC patients." (PMID 36635779, 2023). "High clonotype avidity is specifically associated with tumor residence at steady state, higher CXCR3 expression and tumor engraftment following ACT in mice." (PMID 37280206, 2023). "By IVIS imaging of tumor growth of mice for up to 91 days posttumor, Cxcr3 loss impaired the long-term antitumor activity of αPD-L1 + CD40 agonist." (PMID 36472588, 2023). "Effective tumor infiltration in mice models is associated with high structural avidity and CXCR3 expression." (PMID 37280206, 2023). "Since the triple treatment caused a strong expansion of CXCR3+ tumor-specific CD8+ T cells in the blood circulation, we examined the effect of triple treatment on the abscopal effect in mice with two contralateral tumors, where only the primary was irradiated." (PMID 37045833, 2023). "As Cxcr3 is regulated on antigen-specific T cells during PDA growth, we next tested if Cxcr3 deficiency impacted tumor growth and T cell infiltration." (PMID 36472588, 2023). "This is surprising, as these two immune cell populations are commonly associated with CXCR3 and its ligands, and one would expect the increased recruitment of these immune cells to the tumor site." (PMID 38104126, 2023). "CLEC9A and CXCR3 are associated with intratumoral dendritic cells (DCs), which are necessary for anti-tumor immunity." (PMID 36583019, 2022). "This dual anti-tumor and pro-tumor effect seems to be closely related to CXCR3 variants (CXCR3-A, CXCR3-B, and CXCR3-alt), which play different roles." (PMID 36479091, 2022). "Recent studies have revealed that the chemokine receptor CXCR3 and its ligands are not only expressed in immune cells but are also highly expressed in a variety of tumor cells, and its different variants have very different biological effects on tumors." (PMID 36479091, 2022). "Overall, we found that CXCR3 ligands was associated with an increased number of T cells in tumor rich areas and that CAFs downregulated the expression of CXCR3 on T cells." (PMID 35954489, 2022). "Most likely, the implicated tumor-promoting effects of CXCR3 can be explained by the tumor cell autonomous expression of this chemokine receptor and its described positive impact on cancer cell motility, resulting in an increased metastasis-forming capacity." (PMID 36428508, 2022). "CXCL9-expressing tumor-associated macrophages can recruit a large number of CXCR3-expressing stem-like CD8+ T cells into TME, thus improving the efficacy of anti-PD(L)-1 treatment." (PMID 36090326, 2022). "Conversely, CXCL10 signalling via CXCR3 isoforms overexpressed upon transformed cells is implicated in the growth, invasion and metastasis of several tumour types." (PMID 35844527, 2022). "Previous studies have shown that tumor infiltration of activated T cells and NK cells is significantly reduced in mice deficient in CXCR3, the receptor for CXCL9 and CXCL1032." (PMID 36266311, 2022).
tumor (continued). "CXCR3 (C-X-C motif chemokine receptor 3) participates in tumorigenesis and promotes the formation of tumor-associated blood vessels by binding to its cognate CXC chemokine ligand 9(CXCL9)/10/11." (PMID 36479091, 2022). "CXCR3-expressing tumor-associated endothelial cells exert anti-tumorigenic effects and have been described as anti-proliferative and pro-apoptotic in renal cancer, breast cancer and myeloma." (PMID 35897689, 2022). "CXCR3 has been widely implicated in various diseases like diabetes, vitiligo, tumor progression, and cancer, which have been extensively reviewed elsewhere." (PMID 35794867, 2022). "Activation and recruitment of Th17 cells is mediated by stromal tumor-associated fibroblasts and tumor-derived chemokines (CXCR3)." (PMID 35873158, 2022). "In support of this, administration of the hematopoietic growth factor, IL-7, caused increased CXCR3 expression on tumor-associated T cells and immune cell infiltration and decreased tumor burden." (PMID 36164329, 2022). "Blocking CXCL10/CXCR3 signaling results in a loss in M1 polarized macrophages, shifting macrophage populations to a tumor-promoting phenotype." (PMID 35493517, 2022). "This analysis revealed significant CXCR3 expression patterns associated with survival and differential expression between the tumor and adjacent normal tissue." (PMID 34440489, 2021). "Conversely, high expression of CXCL10 and CXCR3 in the tumor microenvironment has been shown to be associated with a poor prognosis in human PDAC in several studies." (PMID 34203869, 2021). "Comparison across samples which showed that CXCR3 expression positively correlates with the abundance of tumor-associated leukocytes (TAL)." (PMID 34440489, 2021). "The tumor-driven changes influenced the expression of the CXCR3 variants and their ligands promote cancer progression, which were worthy of further investigation." (PMID 33585188, 2020). "CXCR3 is upregulated upon activation, and by loss of TGFβ-mediated suppression, which allows for better homing to CXCR3 ligands produced in the tumor microenvironment endogenously and enhanced following radiation." (PMID 32273499, 2020). "In our study, we observed that the expression of CXCR3 was up‐regulated in cluster 4 (mainly from tumours of patients with Notch pathway mutations) compared with cluster 0 (mainly from tumours of non‐mutation patients) of CD8+ T cells." (PMID 32924269, 2020). "Several studies have shown that the expression level of CXCR3 and its ligands was significantly elevated in systemic high-dose interleukin-2 (IL-2) therapy, which suggests the promotion of tumor-specific immunity and association with prognosis." (PMID 32089645, 2020). "Recent studies have shown that the expression of CXCR3 on tumor-specific CD8+ T cells is associated with a better survival of patients with advanced metastatic melanoma." (PMID 32503584, 2020). "Elevated serum CXCL10 and increased expression of CXCL10 and CXCR3 in tumor cells have been associated with a poor prognosis and metastasis." (PMID 32245422, 2020). "A greater increase in serum CXCL10 was associated with longer OS (p = 0.0002), tumor shrinkage (p = 0.003), and greater transient reduction in peripheral CXCR3+ CD8+ T cells (p = 0.001)." (PMID 32046729, 2020). "Conversely, tumor-driven changes in the expression of the CXCR3 variants and their ligands promote cancer progression (autocrine axis)." (PMID 31216755, 2019). "Our work demonstrated that CXCR3 expression was associated with tumor-infiltrating immune cells, which showed a positive association with immune infiltration of T cells CD8, macrophages M1, plasma cells, and NK cells activated." (PMID 31696204, 2019). "This review summarizes the anti- and pro-tumoral activities of the CXCR3 variants and their associated chemokines with a focus on the understanding of their distinct biological roles in the tumor microenvironment." (PMID 31216755, 2019).
tumor (continued). "On the other hand, activation of CXCR3 was associated with poor patient survival in several tumors due to its expression on tumor cells and on regulatory immune cell populations." (PMID 31699153, 2019). "Various cancers evolve mechanisms to shift the CXCR3 variant expression levels towards ratios that are more beneficial for tumor maintenance or progression." (PMID 31216755, 2019). "It has been reported that CXCR3 deficiency correlates with infiltration of macrophage M2 and enhances tumor progression in breast cancer." (PMID 31240220, 2019). "Although the mechanism controlling the alternative splicing of both CXCR3 variants remains to be elucidated, numerous data on their signaling pathways and their respective contribution in tumor development and immunity have been generated." (PMID 31216755, 2019). "Herein, we showed that the number of NK cells at the tumor growth site can be increased by Cxcr3 deficiency with beneficial effect on the anti-tumor efficacy of transferred activated NK cells." (PMID 31699153, 2019). "On the other hand, Cxcr3 deficiency had minimal effects on IL-12/15/18-activated NK cells anti-tumor activity in vivo." (PMID 31699153, 2019). "On the one hand, it was shown that tumor cells can manipulate the expression of the CXCR3 variants in a way that is overall more beneficial for their maintenance." (PMID 31216755, 2019). "The relative expression of CXCR3 variants is important for regulating proliferation and survival in several cancer cells and correlates with tumor dissemination and metastasis." (PMID 29416784, 2018). "These chemokines act via CXC receptor (CXCR) 3 to stimulate trafficking of CXCR3-positive T cells to tumor sites and associated draining lymph nodes, important steps in antitumor immunity." (PMID 30500835, 2018). "The increase of CXCR3A and CXCR3B protein levels between control and benign tumor tissue suggests a neoplastic transformation role for the CXCR3 variants profile." (PMID 29416784, 2018). "High expression of CXCR3 in tumor cells (3+) was associated with markedly reduced PFS both in the discovery set (11 vs 16 months, P=0.045) and in the validation set (11 vs 22 months, P=0.001)." (PMID 28504691, 2017). "Our results suggest that the prostate possesses a unique environment that supports the local production of CXCL10, which is critical for the attraction of CXCR3+ effector cells to tumor-associated TLO." (PMID 28567040, 2017). "This is the first observation of tumor engraftment in CXCR3-deficient hosts and evidence that CXCR3+ monocytes are necessary cellular mediators of transmigration for circulating tumor cells to infiltrate the lung compartment." (PMID 28358049, 2017). "The importance of tumor-encoded Cxcr3 in promoting metastatic chemotaxis and cancer progression has been well documented." (PMID 29050279, 2017). "Systemic blockade of CXCR3 signaling with AMG487 in WT mice abrogated tumor-associated increases in monocyte and macrophage numbers in lungs (respectively), but not in spleen." (PMID 28358049, 2017). "CXCR3 encodes the chemokine (C-X3-C motif) ligand protein; studies have shown that CXCR3 deficiency speeds tumor progression, and that CXCR3 isoforms have divergent roles in promoting cancer stem-like cell survival and metastasis." (PMID 27467526, 2016). "In other situations of inflammation or tumor, CXCR3, ChemR23, and CCR6 are implicated to be involved in pDCs migration to periphery tissues." (PMID 24734242, 2014). "This surrounding area was also positive for CXCR3, while mRNAs encoding Mig and IP-10, the ligands of CXCR3 and T-cell chemoattractants, were strongly expressed in the tumor itself." (PMID 25123545, 2014). "It has been shown that a subpopulation of the FOXP3+ T-regulatory cells, which express CXCR3, is more prevalent among the tumor associated as well as tumor infiltrating lymphocytes." (PMID 24384839, 2013).